BDP1 (BDP1 general transcription factor IIIB subunit)
Description:
General activator of RNA polymerase III transcription. Requires for transcription from all three types of polymerase III promoters. Requires for transcription of genes with internal promoter elements and with promoter elements upstream of the initiation site.
Synonyms: TFIIIB150; KIAA1241; KIAA1689; TFNR; TFC5; HSA238520; DFNB112; TAF3B1; TFIIIB''; TFIIIB90
Tractability: Small molecule: a structure with a bound ligand is known. PROTAC: ubiquitination databases record sites on it.
Gene: Protein-coding gene on chromosome 5 (71,455,651 to 71,567,820, forward strand). Ensembl gene ENSG00000145734.
Subcellular location: Nucleus
Subcellular location (Human Protein Atlas): Nucleoplasm
Pathways (Reactome):
Gene expression (Transcription): RNA Polymerase III Abortive And Retractive Initiation; RNA Polymerase III Transcription Initiation From Type 1 Promoter; RNA Polymerase III Transcription Initiation From Type 2 Promoter; RNA Polymerase III Transcription Initiation From Type 3 Promoter
Gene Ontology:
Molecular function: protein binding; TFIIIC-class transcription factor complex binding
Biological process: positive regulation of transcription by RNA polymerase III; RNA polymerase III preinitiation complex assembly
Cellular component: nucleoplasm; transcription factor TFIIIB complex; nucleus
Genetic constraint (gnomAD): Loss-of-function variants: 121 observed, 205.98 expected, observed/expected ratio (o/e) 0.59, 90% interval 0.51 to 0.68. The upper end of that interval is the gene's LOEUF score, 0.68, which puts it in group 2 of 6, group 1 being the genes least tolerant of losing a copy. Missense variants: 2,462 observed, 2,653.9 expected, observed/expected ratio (o/e) 0.93, 90% interval 0.9 to 0.96. Synonymous variants: 914 observed, 905.82 expected, observed/expected ratio (o/e) 1.01, 90% interval 0.95 to 1.07.
Gene-disease validity (ClinGen):
ClinGen rates the evidence that BDP1 causes each of these diseases.
nonsyndromic genetic hearing loss (autosomal recessive): Limited.
Homologues: Orthologues: chimpanzee BDP1 (98% identical), macaque BDP1 (92% identical), dog BDP1 (66% identical), pig BDP1 (63% identical), mouse Bdp1 (52% identical), rat Bdp1 (51% identical), tropical clawed frog bdp1 (20% identical), zebrafish zgc:162472 (7% identical), zebrafish bdp1 (6% identical), Caenorhabditis elegans vep-1 (5% identical), Drosophila melanogaster Bdp1 (5% identical).
Diseases named in the same sentence as BDP1 in open-access papers:
BDP1 is named in the same sentence as 30 diseases in open-access papers, as found by Europe PMC text mining. Sharing a sentence is not in itself a finding about the gene and the disease. The quoted sentences say what the papers report.
breast carcinoma (10 papers, 2015 to 2023). "Specifically, Professor Laura Schramm pointed out that our article miscited Gensler’s study entitled “Negative Regulation of HER2 Signaling by the PEST-type Protein-tyrosine Phosphatase BDP1” as evidence for the TFIIIIB-associated BDP1 subunit playing a pivotal role in breast cancer." (PMID 35328170, 2022). "We queried all breast cancer datasets housed in the OncomineTM Research Platform (277 samples) to determine if BDP1 copy number or mRNA expression is altered in breast cancer and if BDP1 alterations correlated with clinical outcomes in breast cancer." (PMID 35406430, 2022). "The manuscript attempted to energize the novelty of BDP1 in neuroblastoma, even though the concept of BDP1’s cancer-involved is emerging with colorectal cancers, lung cancer, and breast cancer." (PMID 35328170, 2022). "The objective of this study was to analyze publicly available clinical cancer datasets to determine if BDP1 alterations correlate with clinical outcomes in available breast cancer datasets." (PMID 35406430, 2022). "Herein, we analyzed clinical breast cancer datasets to determine if BDP1 alterations correlate with clinical outcomes." (PMID 35406430, 2022). "BDP1 copy number and expression negatively correlate with breast cancer outcomes, including stage, grade, and mortality." (PMID 35406430, 2022). "Together, these data suggest a role for BDP1 as potential biomarker in breast cancer and additional studies are warranted." (PMID 35406430, 2022). "Using Oncomine, we performed a perturbation analysis of breast cancer datasets available to potentially identify chemotherapeutic agents regulating BDP1 mRNA expression." (PMID 35406430, 2022). "The manuscript attempted to energize the novelty of BDP1 in N.B., even though the concept of BDP1’s cancer-involved is emerging with colorectal cancers, lung cancer, and breast cancer." (PMID 34943600, 2021). "The functional genomics approach to investigating BDP1 alterations in breast cancer is significant." (PMID 35406430, 2022). "Together, the data presented in this study suggest that BDP1 may be a novel target for therapeutic intervention for patients with breast cancer, and larger studies are warranted." (PMID 35406430, 2022). "Together, these data prompted us to determine if available public datasets provide insight into whether BDP1 is a potential therapeutic target in breast cancer." (PMID 35406430, 2022). "Additional studies are warranted to determine if BDP1 may be a novel target for breast cancer therapy." (PMID 35406430, 2022). "Hence, we examined if BDP1 alterations correlated with clinical outcomes in breast cancer." (PMID 35406430, 2022). "BDP1 mRNA expression correlates with ER and PR receptor expression in patients with metastatic breast cancer occurring three-year post-diagnosis, patients with breast cancer recurring three years post initial diagnosis and correlated with death after three years and five years." (PMID 35406430, 2022). "The results of this study suggest that PIs efficiently inhibit ERα/HER2 cross-talk pathways through blocking ERα expression, as well as through inhibiting HER2 activation via stabilization of BDP1, which leads to the death of ER+/HER2+ breast cancer cells." (PMID 29069787, 2017). "Together these results suggest that PIs efficiently inhibit ERα/HER2 cross-talk pathways through blocking ERα expression, as well as through inhibiting HER2 activation via stabilization of BDP1, which leads to the death of ER+/HER2+ breast cancer cells." (PMID 29069787, 2017). "PIs on the other hand affect HER2+ breast cancer cells through multiple mechanisms and counteract HER2 activation through different mechanisms compared to TKIs for example through stabilizing the PEST-type protein tyrosine phosphatase BDP1 as we show here." (PMID 29069787, 2017).
breast carcinoma (continued). "The expression of TFIIIB components BRF1, BRF2 and BDP1 was in tendency higher in luminal subtypes, that of most TFIIIC components (C2-C6) in Her2-overexpressing cancer, but none of these general Pol III transcription factors showed increased expression levels in basal breast cancers." (PMID 36497214, 2022). "To date, the TFIIIB specific subunit BDP1 has not been investigated in ovarian cancer but has previously been shown to be deregulated in neuroblastoma, breast cancer, and Non‐Hodgkins lymphoma." (PMID 36305848, 2023).
neuroblastoma (4 papers, 2021 to 2023). Neuroblastoma (NB) is the most common solid, extracranial childhood tumor. "Recently, BDP1 alterations in human cancers have been identified, including BDP1 somatic frameshift mutations in colorectal cancer, n = 98 and two BDP1 variants associated with poor clinical outcomes in neuroblastoma." (PMID 36305848, 2023).
colorectal cancer (3 papers, 2021 to 2023). A primary or metastatic malignant neoplasm that affects the colon or rectum. "Specifically, in colorectal cancer, BDP1 somatic frameshift mutations were identified, n = 98, but clinical outcome data were not reported." (PMID 36305848, 2023). "We noticed that there is functional overlap of both PTPN18 and BDP1 in colorectal cancer." (PMID 35328170, 2022).
deafness (3 papers, 2013 to 2021). An inherited or acquired condition characterized by the complete loss of the ability to hear from one or both ears. "Additional biochemical and functional studies as well as an appropriate mouse model are required to understand better the molecular mechanisms underlying deafness associated with BDP1 mutations." (PMID 24312468, 2013). "The other 6 variants were associated with recessive forms of deafness (TMPRSS3, GPSM2, BDP1, EPS8, EPS8L2, and PCDH15)." (PMID 33809266, 2021). "Conclusive proof of the involvement of the BDP1 gene in hearing loss will require the finding of additional mutations in other families associated with deafness or evidence from animal models with Bdp1 mutations, but these are not yet available." (PMID 24312468, 2013).
hearing loss (3 papers, 2013 to 2025). "Two non-syndromic hearing loss (NSHL) genes (BDP1 and MYO6) were reported in two separate families in South Africa, suggesting a possible phenotypic expansion." (PMID 41516007, 2025). "Normothermia TTM upregulated 13 genes associated with hearing loss, including Loxhd1, Tecta, Zmiz1, Espn, Gjb2, Sesn3, Bdp1, Hg, Pax3, Rnls, Syne4, P2rx2, and Pou3f4." (PMID 38298897, 2023). "In addition, variants in two non-syndromic hearing loss (NSHL) genes (BDP1 and MYO6) were reported in two independent South African families with WS features, suggesting a possible phenotypic expansion." (PMID 41516007, 2025). "Moreover, as inherited hearing loss is a highly heterogeneous trait and there are many genes involved that have not yet been identified, the BDP1 gene could be involved in HHL in other populations as well as in the Qatari population." (PMID 24312468, 2013). "The BDP1 gene maps in a hearing loss locus DFNB49, 2Mb away from MARVELD2, a gene already known to be involved in hearing loss but containing no predicted pathogenic mutations in this family." (PMID 24312468, 2013).
malaria (2 papers, 2021 to 2022). Malaria is a serious and sometimes fatal disease caused by a parasite that commonly infects a certain type of mosquito which feeds on humans. "In conclusion, we identified PfBDP7 as a chromatin binding protein that is a constitutive part of the P. falciparum BDP1/BDP2 core complex and established PfBDP1 and PfBDP7 as novel players in the silencing of heterochromatin regulated virulence gene families of the malaria parasite P. falciparum." (PMID 35493110, 2022). "These proteins include the bromodomain protein 1 (BDP1), HP1, and other AP2 family TFs, suggesting that the PfGCN5 complex may have broader functions in chromatin biology in the malaria parasite." (PMID 34403450, 2021).
invasive breast carcinoma (1 paper, 2022). A carcinoma that infiltrates the breast parenchyma. "Together, the data presented suggest a role for BDP1 alterations in invasive breast cancer." (PMID 35406430, 2022). "Taken together, these data suggest a role for BDP1 alterations in invasive breast cancer." (PMID 35406430, 2022). "Interestingly, decreased BDP1 expression correlated with clinical outcomes (n = 295 samples): a metastatic event at three years (p = 7.79 × 10−7) and cancer reoccurrence at three years (p = 4.81 × 10−7) in patients with invasive breast cancer (IBC)." (PMID 35406430, 2022).
invasive ductal carcinoma (1 paper, 2022). "BDP1 copy number (n = 1602; p = 8.03 × 10−9) and mRNA expression (n = 130; p = 0.002) are specifically decreased in patients with invasive ductal carcinoma (IDC)." (PMID 35406430, 2022). "Specifically, we report that BDP1 copy number (n = 1602; p = 8.03× 10−9) and mRNA expression (n = 130; p = 0.002) are decreased in patients with invasive ductal carcinoma (IDC)." (PMID 35406430, 2022). "Herein, we report that BDP1 copy number (n = 1602; p = 8.03 × 10−9) and mRNA expression (n = 130; p = 0.002) are specifically decreased in patients with invasive ductal carcinoma (IDC)." (PMID 35406430, 2022).
ovarian carcinoma (1 paper, 2023). A malignant neoplasm originating from the surface ovarian epithelium. "The identification of NCOR2 as one of the top eight genes responding to combination therapy in ovarian cancer is significant because like BDP1, NCOR2 contains a SANT domain." (PMID 36305848, 2023). "BDP1 mRNA expression was significantly decreased in ovarian cancer, p = 0.01 but the expression of other TFIIIB subunits, BRF1, BRF2, and TBP, was not significantly changed." (PMID 36305848, 2023). "BDP1 alterations negatively impacted disease‐free progression in patients with ovarian cancer (p = 0.0271, q = 0.0542)." (PMID 36305848, 2023). "Using this approach, we report that the BDP1 alterations identified in ovarian cancer were deep deletions with decreased expression correlating with increased serous ovarian cancer stage similar to known critical cancer drivers, BRCA1 and BRCA2." (PMID 36305848, 2023). "Thirty genes were significantly co‐expressed with BDP1 in ovarian cancer based on the q‐value derived from the Benjamini–Hochberg FDR correction procedure and Spearman's coefficient cutoff value of 0.5." (PMID 36305848, 2023). "The primary aim of this study was to determine if the TFIIIB subunit BDP1 is specifically altered in ovarian cancer and if the observed alterations correlate with clinical outcomes." (PMID 36305848, 2023). "Using the cBioPortal, we performed an analysis for genes co‐expressed with BDP1 in the TGCA ovarian cancer dataset, using Spearman's correlation coefficient cutoff value of 0.5." (PMID 36305848, 2023). "The major advantage of using multiple bioinformatics platforms that utilize clinical samples to analyze BDP1 in ovarian cancer is that each platform employs various algorithms to determine statistical significance and confirm results using multiple analyses." (PMID 36305848, 2023). "These BDP1 alterations negatively impacted disease‐free progression in patients with ovarian cancer as well." (PMID 36305848, 2023). "These recent BDP1 clinical cancer studies prompted our investigation of BDP1 alterations and expression in ovarian cancer." (PMID 36305848, 2023). "Using open‐access clinically derived platforms, we analyzed BDP1 alterations in ovarian cancer samples in silico." (PMID 36305848, 2023). "Similarily, BDP1 expression significantly decreased (p = 4.1 × 10−4) in ovarian cancer patient's treated with taxane, and ROC analysis (p = 1.1 × 10−04, AUC = 0.616)." (PMID 36305848, 2023). "To gain additional insight regarding the network BDP1 alterations affect in the context of ovarian cancer, we performed a gene ontology analysis of genes co‐expressed with BDP1." (PMID 36305848, 2023). "In line with a dual role for BDP1 dependent on the mutational profile of the cancer, we recognize that ovarian cancer cells depend on MYC for maintaining their oncogenic growth and is amplified in 30–60% of all ovarian cancers." (PMID 36305848, 2023). "The identification of NCOR2 as one of the top eight genes responding to combination therapy in ovarian cancer is significant because like BDP1, NCOR2 contains a SANT domain (SWI3, ADA2, N‐Cor, and yeast TFIIIB BDP1 proteins) (reviewed in17)." (PMID 36305848, 2023).
ovarian serous cystadenocarcinoma (1 paper, 2023). A malignant serous cystic epithelial neoplasm arising from the ovary. "Using the cBioPortal platform, we queried the TCGA Ovarian Serous Cystadenocarcinoma dataset (TCGA, Firehose Legacy),40n = 594 patients, for BDP1 alterations." (PMID 36305848, 2023).
prostate carcinoma (1 paper, 2022). A carcinoma that arises from epithelial cells of the prostate gland. "A study implicating BDP1 in prostate cancer was performed in a PTEN-null prostate cancer cell line." (PMID 35406430, 2022).
serous ovarian carcinoma (1 paper, 2023). "This is the first study to implicate BDP1 in serous ovarian cancer and the first study to demonstrate varied expression for BDP1 in human cancer dependent on the mutation profile." (PMID 36305848, 2023). "Using the Kaplan–Meier Plotter48 web portal, we analyzed both BDP1 expression and survival in serous ovarian cancer." (PMID 36305848, 2023). "Taken together, this suggests that BDP1 is behaving similarly to an already established biomarker of serous ovarian cancer, NCOR2, in clinical samples treated with chemotherapies platin and taxane." (PMID 36305848, 2023). "Using in silico analysis of clinically derived platforms, we report a decreased BDP1 expression as a result of deletion in serous ovarian cancer and a correlation with higher and advanced ovarian stages." (PMID 36305848, 2023). "We analyzed BDP1 expression in response to common serous ovarian cancer chemotherapies and at twelve‐month relapse‐free survival in patients treated with platin, BDP1 expression significantly decreased (p = 3.2 × 10−05)." (PMID 36305848, 2023). "Only the TFIIIB subunit BDP1 exhibited significantly decreased expression in serous ovarian cancer as the stage increased (F = 8.06; Pr(>F) = 3.66 × 10−4)." (PMID 36305848, 2023). "We sought to determine if the observed alterations in BDP1 in serous ovarian cancer are unique to BDP1 or are a common feature in all TFIIIB subunits including, BRF1, BRF2, and TBP which have been previously shown to be deregulated in cancer." (PMID 36305848, 2023). "Together, these data suggest potential cross‐talk between BRCA1 and BDP1 activity in late‐stage serous ovarian cancer as a component of the oncogenic network driving proliferation." (PMID 36305848, 2023). "We queried the GEPIA platform using the TCGA serous Ovarian Serous Cystademocarcinoma and GTEx gene expression datasets to analyze BDP1 expression across stages in serous ovarian cancer." (PMID 36305848, 2023). "Together, our data suggest BDP1 expression is deregulated in serous ovarian cancer with clinical samples demonstrating BDP1 may be both over‐ and under‐expressed, suggesting dual function for BDP1." (PMID 36305848, 2023). "Thus, we investigated the possibility of BDP1 as a predictive biomarker for chemotherapy treatment in serous ovarian cancer using the ROC plotter platform." (PMID 36305848, 2023). "Taken together, this potentially suggest a key role for BDP1 in serous ovarian cancer." (PMID 36305848, 2023). "The ROC analysis (p = 6.6 × 10−06, AUC = 0.618) suggests BDP1 may be a predictor of a serous ovarian cancer patient's response to platin‐based chemotherapy." (PMID 36305848, 2023). "Taken together with a ROC analysis, the data suggest BDP1 could be of clinical relevance as a predictive biomarker in serous ovarian cancer." (PMID 36305848, 2023). "Interestingly, BDP1 expression decreased as serous ovarian cancer stage similar to BRCA1 (F = 3.81; Pr(>F) = 2.3 × 10−2) and BRCA2 (F = 12.8; Pr(>F) = 3.95 × 10−6)." (PMID 36305848, 2023).